MMP8 (matrix metallopeptidase 8)
Diseases named in the same sentence as MMP8 in open-access papers (continued):
Sharing a sentence is not in itself a finding about the gene and the disease.
Sepsis (continued). "Our study specifically highlights the differential expression of matrix metalloproteinases (MMPs), such as Mmp2-3, Mmp8-9, Mmp14, Mmp17, Mmp19, and Mmp28-29, with significantly higher expression in LPS-induced sepsis compared to CLP-induced sepsis." (PMID 37510271, 2023). "The concentrations of the proteins S100A8, MMP8, CSF3, and IL-6, were measured in peripheral blood samples from 31 sepsis patients to validate the critical extracellular proteins identified in the study." (PMID 37901226, 2023). "In a prospective study including 68 newborns with early-onset sepsis (EOS) and 83 newborns as a control group, it was demonstrated that IL-6, TNF-α, HSP70, PCT, and CRP together with MMP-8 can be used as a predictive biomarker of EOS." (PMID 36613805, 2022). "In conclusion, the present study revealed an unbalanced immune response at the transcriptome level of sepsis and identified genes for potential biomarkers of sepsis, such as ITK, CD247, MMP9, CD3D, MMP8, KLRK1, and GZMK." (PMID 35190763, 2022). "Not only this, but MMP‐8 levels have also been evidenced to be increased alongside MMP‐9, MMP‐2, and TIMP‐1 during early sepsis, a condition which has eventually been related to patient mortality." (PMID 35818743, 2022). "The present study observed significantly higher early MMP-8 (day 3 and 5) and TIMP-1 (day 3) levels among patients with severe sepsis, high Pitt bacteremia scores and ICU treatment compared to patients without severe illness or need for ICU." (PMID 34043679, 2021). "Higher MMP-2, MMP-8, MMP-9, MMP-10, TIMP-1 and MMP-10/TIMP-1 were seen in severe sepsis compared to controls." (PMID 34043679, 2021). "Matrix metalloproteinase-8 (MMP-8) and tissue inhibitor of metalloproteinases-1 (TIMP-1) have been shown to predict prognosis in sepsis." (PMID 34043679, 2021). "Genes that were expressed at high levels in MBC and sepsis patients compared with HC N cells were relevant to immunosuppression and metastasis (ARG1, MMP8, TLR5, and CD177) (green)." (PMID 32958605, 2020). "Some selected genes were significantly higher expressed in sepsis as compared with MBC samples (CD24, CD177, MMP8, and TLR5), and in MBC compared with sepsis (HLA-DRA, CSF1R, and AGAP6/9)." (PMID 32958605, 2020). "Gene differential expression analysis between healthy controls and sepsis showed that genes such as ARG1, CD177, MMP8 and C19orf59 were upregulated." (PMID 33032623, 2020). "Elevated matrix metalloproteinase-8 (MMP-8) activity contributes to the etiology of many diseases, including atherosclerosis, pulmonary fibrosis, and sepsis." (PMID 32784891, 2020). "Subsequently, MMP-8 knockout mice demonstrated increased survival compared to wild-type animals when subjected to the cecal ligation and puncture (CLP) model of sepsis." (PMID 31461880, 2019). "The association of the MMP-1 (-1607 1G/2G) SNP and sepsis might be due to linkage disequilibrium with the MMP-13 SNP because the MMP-13 and MMP-1 genes are both located in the same cluster of the chromosome 11q22-23 along with the MMP-3, MMP-7, MMP-8, MMP-10, MMP-12, and MMP-20 genes." (PMID 24833564, 2014). "In severe sepsis, from intact skin suction blister and serum samples, MMP-2 and MMP-8 levels are elevated, whereas MMP-9 is suppressed." (PMID 20356362, 2010). "We measured the MMP-2, MMP-8 and MMP-9 levels during human severe sepsis and after recovery in serum and locally in skin using the suction blister method." (PMID 20356362, 2010). "This is the first longitudinal study reporting the levels of MMP-2, MMP-8 and MMP-9 in the patients with severe sepsis." (PMID 20356362, 2010). "Our findings reveal markers of the microvascular response to sepsis, which include increased levels of HP, C3, Chil3/CHI3L1, and MMP8, both at the transcriptomic level in mouse and human kidney microvasculature and at the protein level in circulating plasma of SA-AKI patients." (PMID 40892345, 2025).
Sepsis (continued). "Therefore, all measured proteins showed elevated circulating plasma levels in patients with sepsis or SA-AKI, with CHI3L1 and MMP8 having distinguishably higher levels in SA-AKI compared to sepsis in both early-stage sepsis and advanced-stage sepsis." (PMID 40892345, 2025). "Besides, Ureaplasma infection increased the infiltration of inflammatory cells, releasing cytokines of interleukin 6 (IL-6), matrix metalloproteinase 8 (MMP8), tumour necrosis factor α (TNFα) and contributing to late-onset sepsis (LOS)." (PMID 37365524, 2023). "This leads us to believe that blood levels of MMP8 and S100A8 may be valuable biomarkers of sepsis-related brain damage." (PMID 37901226, 2023). "After examining the levels of MMP-8 expression in non-oncological illnesses, noteworthy distinctions were discovered in severe asthma, pneumonia, and sepsis (|Log2Fold-Change|> 1 and P < 0.05)." (PMID 37464428, 2023). "In our study, decreased serum levels of 25(OH) D neither correlated with MMP-8 levels nor with the incidence of early sepsis or LOS in PTs at any of the three-time points." (PMID 36639750, 2023). "In addition, MMP8 and MMP9 inhibitors have been shown to have significant effects on improving BBB permeability in mice after sepsis." (PMID 36445634, 2023). "Prevalence of MMP8 rs11225395 G/G genotype was higher in sepsis patients than in those with non-infective Systemic Inflammatory Reaction Syndrome (35.6 vs. 26%, hazard ratio, HR 1.56, 95% C.I. 1.04–2.42, p = 0.032)." (PMID 35204780, 2022). "Additionally, serum levels of MMP-8 and TIMP-1 were correlated with mortality in patients with sepsis." (PMID 36142454, 2022). "MMP-8 and MMP-8/TIMP-1 ratio were high 3–5 days after MS-SAB diagnosis in patients with an infection focus, severe sepsis or mortality within 14 days suggesting that matrix metalloproteinase activation might play a role in severe SAB." (PMID 34043679, 2021). "Fourth, neither MMP-8 nor elastase-2 has been studied formally in AKI disease pathogenesis, from sepsis or other causes." (PMID 22098946, 2011). "• Levels of MMP-2 and MMP-8 were up-regulated in severe sepsis in comparison with healthy controls, both in skin blister fluid and in the serum, whereas MMP-9 levels were lower in serum in sepsis from the fourth day onwards." (PMID 20356362, 2010). "Our studies did not reveal the source, but demonstrate, that in severe sepsis MMP-8 is up-regulated even in healthy looking skin." (PMID 20356362, 2010). "Considering the ability of MMP8 in upregulating the expression of VCAM-1, and the over adhesion of leukocyte to endothelium in sepsis, we hypothesized that sepsis serum promotes leukocyte adhesion to endothelium via MMP8 in sepsis." (PMID 35145983, 2022). "We bring forward now the potential role of collagenases (MMP-13 and MMP-1) and perhaps stromelysins (MMP-3) in sepsis, an interesting finding because these MMPs are neither expressed in neutrophils nor released from neutrophils granules after endotoxin challenge as MMP-8 and MMP-9 do5." (PMID 24833564, 2014). "MMP8 and S100A8 levels in the peripheral blood of sepsis patients were higher in SAE than in non-SAE." (PMID 37901226, 2023). "Consistently, for MMP-8 rs11225395, HW was not confirmed in all groups of patients (p = 0.02, 0.0022, and 0.039 for non-infective SIRS, sepsis, and undefined patients, respectively)." (PMID 35204780, 2022). "Previous reports have observed higher MMP-8 on and TIMP-1 at sepsis onset or ICU admission in non-surviving sepsis patients compared to surviving ones." (PMID 34043679, 2021). "Cross tabulation of genetic prevalence was marginally significant only for MMP-8 (codominant model), although MMP-8 G/G genotype (recessive model) was more prevalent in sepsis patients than in non-infective SIRS patients (35.6 vs. 26%) with an increase in risk of 58% (95%CI 1.04–2.42)." (PMID 35204780, 2022).
gingivitis (59 papers, 2013 to 2026). A disorder involving inflammation of the gums; may affect surrounding and supporting structures of the teeth. "Patients with gingivitis presented higher salivary MMP-8 levels than healthy individuals (MD = 122.82, CI: 64.19; 181.45)." (PMID 39641024, 2024). "A study revealed that matrix-metalloproteinase 3 (MMP-3), MMP-8, and IL-1β in gingival crevicular fluid and whole saliva of gingivitis patients remained insignificantly altered over 8 weeks of OIs use." (PMID 36834421, 2023). "The combination of IL-1β and MMP-8 exhibited the best ability to discriminate gingivitis from healthy subjects (AUC = 0.84)." (PMID 34001101, 2021). "Further, the combination of IL-1β and MMP-8 can be used to discriminate gingivitis patients from healthy subjects." (PMID 34001101, 2021). "IL-1β, MMP-8, and Pg levels were shown to be significantly different between the gingivitis group and the healthy group." (PMID 34001101, 2021). "Significantly elevated MMP-8 levels in serum were also reported in periodontally healthy women with PCOS in relation to systemically healthy women with gingivitis." (PMID 32456146, 2020). "MPO and MMP-8 levels in saliva were strongly correlated with gingivitis, with Pearson’s correlation coefficients of 0.399 and 0.217, respectively." (PMID 32503210, 2020). "After compensation for gingivitis, gingival pockets and smoking, the mean salivary levels of MMP-8 (543 vs 440 ng/mL, p = 0.003) and MPO (1899 vs 1637 ng/mL, p = 0.02) were higher in non-MI subjects compared to MI patients." (PMID 26132583, 2015). "The aim of the present study was to evaluate the effect of adjunctive chlorhexidine (CHX) mouthrinse on gingival crevicular fluid (GCF) MMP-8 and TIMP-1 levels in plaque-associated gingivitis." (PMID 24886536, 2014). "Similarly, the combination of IL-1β and MMP-8 showed an AUC of 0.84 in differentiating gingivitis from healthy individuals." (PMID 40283051, 2025). "More studies investigated the role of MMP-8 level elevation in gingivitis in different samples." (PMID 39641024, 2024). "Similarly, patients with gingivitis presented significantly higher salivary MMP-8 levels than healthy individuals (MD = 122.82 ng/ml, CI: 64.19; 181.45) based on the results of 10 eligible studies (n = 704)." (PMID 39641024, 2024). "Furthermore, individuals with gingivitis demonstrate a higher salivary MMP-8 level compared to healthy controls." (PMID 39641024, 2024). "Similarly, significantly higher IL-1β and MMP-8 levels were also found in women with gingivitis compared to healthy pregnant women." (PMID 36432584, 2022). "Moreover, the combination of IL-1β and MMP-8 can be used to discriminate gingivitis subjects from healthy subjects." (PMID 35368315, 2022). "To analyze the effect of the treatment on early gingivitis, we performed an MMP-8 analysis." (PMID 34063662, 2021). "Interestingly, elevated levels of both matrix metalloproteinase (MMP)-8 and Treponema denticola were determined between a smaller group of 18 subjects with gingival health and 32 subjects with gingivitis." (PMID 33615769, 2021). "Among various biomarkers, MMP-8 is one of the most sensitive for diagnosing gingivitis." (PMID 34679720, 2021). "The gingivitis group showed higher levels of IL-1β, MMP-8, and Pg compared to the healthy group." (PMID 34001101, 2021). "MMP-8 showed the largest AUC and strongest correlation with gingivitis in this study." (PMID 32503210, 2020). "A slight increase in MMP-8 levels could be observed in case of gingivitis, which shows a decrease after dental prophylaxis or secondary preventive interventions." (PMID 30305812, 2018). "However, MMP-8 and IL-1beta levels were analyzed around teeth and implants during the course of experimental peri-implant mucositis and gingivitis." (PMID 26832782, 2016).
gingivitis (continued). "As shown in our results, a previous study showed lower concentrations of MMP8 in the saliva from juvenile periodontitis patients versus individuals with gingivitis and healthy controls, suggesting that MMP8 could have a systemic protective and anti-inflammatory role." (PMID 33255937, 2020). "However, there are limited data related to the MMP-8 levels in gingivitis patients." (PMID 24886536, 2014). "There were significant differences in the salivary MMP‐8 levels between healthy and gingivitis participants as measured by the biosensor (p < .05), aMMP‐8 IFMA (p < .001), and total MMP‐8 ELISA (p < .001)." (PMID 35304757, 2022). "In their study, levels of interleukin (IL)-1β, IL-6, MMP-8, and PGE2 from 40 periodontally healthy subjects and 40 subjects with gingivitis were measured." (PMID 33615769, 2021). "In our study, change of MMP-8 and MMP-9 in saliva were measured to confirm improvement of gingivitis." (PMID 34679720, 2021). "In conclusion, the present study showed similar levels of MMP‐8, IL‐8 and AGEs in the GCF of T1D and healthy subjects, despite the fact that the diabetic cohort presented slightly higher prevalence of gingivitis (68% vs. 60%)." (PMID 33369174, 2021). "This study demonstrated that the MMP-8 and MPO levels are suitable for diagnosing gingivitis based on significant results obtained in both correlation and ROC curve analyses." (PMID 32503210, 2020). "In terms of MMP-8, levels were found to be significantly higher in women with PCOS and gingivitis than in systemically healthy women with gingivitis." (PMID 32456146, 2020). "In addition, a higher expression of matrix metalloproteinase (MMP)-8 was observed in the serum and saliva of women with comorbidity of PCOS and gingivitis compared with that in systemically healthy individuals with gingivitis." (PMID 36755917, 2023). "This is in agreement and further expands the findings revealing that MMP‐8 is not activated in gingivitis." (PMID 35676762, 2022). "MMP-8 and MPO displayed the greatest sensitivity towards gingivitis." (PMID 35453967, 2022). "MMP-8 and MPO were found to be effective for diagnosing gingivitis." (PMID 32503210, 2020). "In summary, MMP-8 and MPO have now been shown to be effective in diagnosing gingivitis." (PMID 32503210, 2020). "Similarly, no significant phylogenetic similarity was found between samples when grouped by the net changes in proinflammatory cytokine interleukin-8 (IL-8), MMP-8, or MMP-9 between day 1 and day 21 of the experimental gingivitis study." (PMID 29666288, 2018). "On the basis of the present findings, it can be concluded that adjunctive CHX provides no additional benefit over daily plaque control on GCF MMP-8 levels and periodontal parameters except on plaque accumulation at posterior sites in gingivitis patients." (PMID 24886536, 2014). "In this short term, randomized, placebo controlled clinical study, which is a continuation of previously published studies, the effectiveness of CHX as an adjunct to daily plaque control on both clinical and GCF MMP-8 and TIMP-1 levels were evaluated in gingivitis patients." (PMID 24886536, 2014). "Previous studies reported that the mRNA level of MMP-1, but not MMP-8, was increased in inflamed gingiva obtained from patients with severe gingivitis, and that the protein level of MMP-1 in gingival crevicular fluid decreased after phase I periodontal therapy." (PMID 37083725, 2023). "No reduction in GCF MMP-8 levels at 4 weeks in gingivitis patients might be explained by the fact that the presence of interdental plaque on interproximal surfaces and supra and/or subgingival calculus prevent to complete resolution of inflammation." (PMID 24886536, 2014).
Peri-Implantitis (55 papers, 2017 to 2026). An inflammatory process with loss of supporting bone in the tissues surrounding functioning DENTAL IMPLANTS. "Elevated MMP-8 levels in peri-implantitis patients and the high diagnostic accuracy of tests like ImplantSafe and PerioSafe underscore the enzyme's clinical relevance." (PMID 39657936, 2025). "The association between the MMP-8 rs11225395 (T allele) and increased susceptibility to peri-implantitis in a Chinese Han cohort is undermined by methodological limitations, which compromise cross-study comparability." (PMID 41373620, 2025). "MMP-9 is especially tricky to assign a certain role in peri-implantitis, because when the levels are found to be high, together with MMP-8 and -13, there tends to be more bone loss around the diseased implant." (PMID 37232785, 2023). "There is also a statistically significant risk of peri-implantitis in obese patients because of higher C-reactive protein and MMP-8 levels in the serum and PICF." (PMID 37232785, 2023). "In the literature, there is a very limited number of studies focused on the MMP8 gene variants as factors involved in peri-implantitis and implant loss." (PMID 37371608, 2023). "Low MMP-8 levels were associated with periodontal and peri-implantitis health while the upregulation of MMP-8 levels denoted an increased risk for inflammation." (PMID 35163727, 2022). "Periodontal and peri-implantitis diagnostic studies have consistently revealed an aMMP-8 analysis to be more exact than the estimation of total MMP-8 or other biomarkers." (PMID 35757444, 2022). "Exploring the molecular mechanisms underlying MMP-8 activation and its interaction with other biomarkers could provide deeper insights into the pathogenesis of peri-implantitis and help identify potential therapeutic targets." (PMID 39657936, 2025). "This study examined the relationship between specific polymorphisms of the MMP-8 gene (−799C/T, −381A/G, and +17C/G) and peri-implantitis, as well as their correlation with clinical parameters such as the probing depth (PD), clinical attachment loss (CAL), and bleeding on probing (BOP)." (PMID 40423054, 2025). "Consequently, the performance of the MMP-8 diagnostic test for peri-implantitis was evaluated at various cutoff values ranging from 20 to 30 ng/mL." (PMID 39657936, 2025). "Thus far, there is little information about specific polymorphisms of MMP-8 and peri-implantitis, as interest has shifted to the diagnostic ability of MMPs in inflammation." (PMID 37232785, 2023). "In addition, the progression of peri-implantitis has been repeatedly associated with pathologically excessive elevation of MMP-8 in oral fluids." (PMID 28117682, 2017). "Similarly, in peri-implantitis, polymorphisms in cytokine- and matrix-related genes (such as IL-1β, IL-17A, and MMP-8) may exert comparable regulatory effects on gene expression, contributing to dysregulated inflammation and tissue destruction." (PMID 41373620, 2025). "Moreover, MMP-8 has been implicated in bone loss in patients with severe peri-implantitis." (PMID 37545886, 2023). "Recent studies have consistently shown elevated activity of MMP-8 in the peri-implant sulcular fluid (PISF) of patients with peri-implantitis." (PMID 39657936, 2025). "The primary study, along with supporting research, provides further evidence for using MMP-8 as a biomarker in diagnosing and monitoring peri-implantitis." (PMID 39657936, 2025). "MMP-8 is one of the biomarkers used in the identification of peri-implantitis, and a recent meta-analysis of 276 patients found that patients with peri-implantitis had significantly higher MMP-8 levels than patients with healthy implants." (PMID 41002732, 2025). "IL-1β +3954 C/T, ET-1 and IL-1β, MMP-8 rs11225395 (T allele), MMP8 (−799 C/T), and CD14 rs2569190 showed consistent associations with increased peri-implantitis risk, while the results for TNF-α −308 G/A were inconsistent across populations." (PMID 41373620, 2025).